CDH11 (cadherin 11)
Diseases named in the same sentence as CDH11 in open-access papers (continued):
Sharing a sentence is not in itself a finding about the gene and the disease.
atherosclerosis (1 paper, 2023). A disease characterized by the build-up of fatty material and calcium deposition in the arterial wall resulting in partial or complete occlusion of the arterial lumen. "In a mouse model of atherosclerosis, Cdh11 expression was increased in atherosclerotic plaques of ApoE−/− mice." (PMID 37944753, 2023).
benign adenomas (1 paper, 2004). "The LMP tumours in our study expressed N-cad and CDH11 at levels intermediate to adenomas and adenocarcinomas, suggesting an integral role for these cadherins in transformation to a malignant phenotype." (PMID 15471544, 2004). "The intensity of change in expression between the benign adenomas and malignant adenocarcinomas for N-cad and CDH11 were 3.9 and 7.8 fold respectively, and both genes appeared in the list of top 163 differentially expressed genes." (PMID 15471544, 2004).
bladder tumor (1 paper, 2022). "We compared the mRNA expression of CDH11, COL6A3, EDNRA, and SERPINF1 between bladder tumor and neighboring healthy tissues, respectively." (PMID 36595851, 2022).
choriocarcinoma (1 paper, 2014). An aggressive malignant tumor arising from trophoblastic cells. "Additionally, the expression of CDH11 is reduced in choriocarcinoma, a quick growing trophoblastic cancer, implicating CDH11 in the regulation of trophoblast proliferation." (PMID 24963923, 2014).
COVID-19 (1 paper, 2022). A disease caused by infection with severe acute respiratory syndrome coronavirus 2. "Both E-cadherin and cadherin 11, together with β-catenin and p120 showed a normal expression pattern in alveolar epithelial cells and other epithelial cells in COVID-19 patients." (PMID 36405615, 2022). "Immunohistochemical analysis demonstrated constitutive expression of cadherin-11 in normal epithelial cells and a similar pattern of cadherin and catenin expression in epithelial cells from both normal and COVID-19 samples." (PMID 36405615, 2022). "Accordingly, the expression of cadherin 11 in hyperplastic COVID-19 alveolar epithelial cells does not represent the cadherin switching process that initiates EMT." (PMID 36405615, 2022).
diffuse large B-cell lymphoma (1 paper, 2021). "In addition, CDH11 is one of the potential biomarkers of diffuse large B-cell lymphoma (DLBCL) and plays an important role in predicting central nervous system recurrence." (PMID 33442417, 2021).
E. coli infection (1 paper, 2020). "Six genes (CLDN20, PARD6B, CD151, CDH11, CLDN2 and F11R) related to the GO biological process “Cell junction organization” were upregulated by E. coli infection, whereas these genes were not induced by EPS." (PMID 32234079, 2020).
embryonic carcinoma (1 paper, 2020). "Cells lacking CDH11 have increased F-actin cabling, which has previously been linked to the execution phase of cell death and is required for the formation of apoptotic bodies in embryonic carcinoma cells." (PMID 33192560, 2020).
epilepsy (1 paper, 2013). A brain disorder characterized by episodes of abnormally increased neuronal discharge resulting in transient episodes of sensory or motor neurological dysfunction, or psychic dysfunction. "Down-regulation of adhesion molecules, including integrin (ITGB1, ITGB2) and cadherin family members (CDH11) in the peritumoral tissue of the subjects with epilepsy also serve to validate our study, as they have also been found to contribute to the cell biology underlying epileptogeneis." (PMID 23418513, 2013).
esophageal adenocarcinoma (1 paper, 2021). A malignant tumor with glandular differentiation arising predominantly from Barrett mucosa in the lower third of the esophagus. "High expression of NR2F2 in certain gastric and esophageal adenocarcinomas is associated with abnormal expression of cadherin 11, suggesting that the NR2F2-related embryonic pathways in these tumors are reactivated." (PMID 33541291, 2021).
gastric adenocarcinoma (1 paper, 2024). "The CDH11 tumor-suppressor gene is also silenced through promoter hypermethylation in gastric adenocarcinomas and is considered a potential prognostic biomarker associated with malignant behavior." (PMID 38542354, 2024).
Intellectual disability (1 paper, 2022). "In human studies, partial deletion of CDH11 has been reported in a sporadic case of non-syndromic ASD, mild intellectual disability, and attention deficit hyperactivity disorder (ADHD)." (PMID 34523068, 2022).
invasive ductal carcinoma (1 paper, 2014). "CDH11 was expressed at high levels in most invasive ductal carcinoma cells (IDCs)." (PMID 24681547, 2014).
invasive lobular carcinomas (1 paper, 2014). "However, in almost all invasive lobular carcinomas (ILCs) CDH11 expression was limited to the stroma." (PMID 24681547, 2014).
ischemia (1 paper, 2021). A hypoperfusion of the BLOOD through an organ or tissue caused by a PATHOLOGIC CONSTRICTION or obstruction of its BLOOD VESSELS, or an absence of BLOOD CIRCULATION. "Under nonischemic conditions, pericytes expressed Cdh19, Cdh6, Cdh10, Cdh4, Cdh13, and Cdh5; after ischemia, the cadherin genes that were predominantly expressed were Cdh15, Cdh11, Cdh3, and Cdh2." (PMID 33726849, 2021).
Krebs 2 carcinoma (1 paper, 2022). "The obtained data confirmed the strong overexpression of Mreg, Prg4, Col3a1, Selp, Marco, and Fgfr1 genes in Krebs-2 carcinoma, as well as Cdh11, Col4a5, Vcam1, Megf6, Scarf2, Scart1, and Cd14 genes in HH47." (PMID 36555446, 2022).
metabolic syndrome (1 paper, 2021). A cluster of metabolic risk factors for CARDIOVASCULAR DISEASES and TYPE 2 DIABETES MELLITUS. "Experiments have also demonstrated that CDH11 deficiency significantly prevents adipose tissue inflammation and metabolic syndrome in obese mice 80,81." (PMID 33442417, 2021). "Therefore, CDH11 targeting is of great significance in the treatment of adipose tissue inflammation, diabetes and metabolic syndrome." (PMID 33442417, 2021).
microtia (1 paper, 2023). "This study identified CDH11 as a candidate pathogenic gene of microtia and supported the potential key role of CDH11 in craniofacial malformations." (PMID 40226415, 2023). "So the migration ability maybe the predominant factor in the development of microtia associated with down-regulated CDH11." (PMID 40226415, 2023). "Transcriptome sequencing analysis after CDH11 knockdown showed that the HOX family genes occupied the top most DEGs, and with the decrease in CDH11, the HOX family gene expression increased, which provided clues for the follow-up study of the role of CDH11 in the occurrence of microtia." (PMID 40226415, 2023). "Therefore, the present results indicated that CDH11 might be involved in the progression of microtia by regulating the expression levels of HOX family genes." (PMID 40226415, 2023).
Myocardial fibrosis (1 paper, 2023). "IL-6 was a downstream signal molecule of cadherin-11 and had a central role in myocardial fibrosis, and cardiomyocyte hypertrophy, which was mediated by activating the MAPKs and CaMKII-STAT3 pathways." (PMID 37047522, 2023).
neuroblastoma (1 paper, 2022). Neuroblastoma (NB) is the most common solid, extracranial childhood tumor. "Moreover, the neuroblastoma mesenchymal transcriptional signature, repressed after BAF disruption, is determined by a specific super-enhancer configuration, and many of these genes (LOXL2, SNAI2, CDH11, ITGAV) are associated with chromatin repressive events." (PMID 36057593, 2022). "Neuroblastoma-specific mesenchymal transcriptional signature was also repressed after BAF disruption in neuroblastoma cells, involving the epigenetic repression of key regulators of the mesenchymal phenotype, such as SNAI2, CDH11, CDH2, LOXL2 and NOTCH2." (PMID 36057593, 2022).
Osteochondroma (1 paper, 2013). A common, benign cartiliginous neoplasm arising from the metaphysis of bone. "The expression rates of CD44V6, CDH11, and β-catenin were 25.0% (5/20), 70.0% (14/20), and 20.0% (4/20) in osteochondroma specimens, respectively." (PMID 23971040, 2013). "Of the osteochondroma cases, diffuse expression of CD44V6 was observed in 5 cases (25.0%), CDH11 in 14 cases (70.0%), and β-catenin in 4 cases (20.0%)." (PMID 23971040, 2013).
otitis media (1 paper, 2019). Inflammation of the anatomical structures of the middle ear, which is most often caused by an infectious process. "In the Cdh11 KO mouse, otitis media is associated with retained mesenchymal cells, and this may occur by altering the proportion of ciliated and non-ciliated epithelium and thereby predisposing to infection." (PMID 30898767, 2019).
squamous cell carcinoma (1 paper, 2012). A carcinoma arising from squamous epithelial cells. "As expected, many of the genes in this list were markers of squamous cell carcinoma (the tumor of origin for the cell line used in this study) such as Cdh11, Postn, and Tnc." (PMID 22927920, 2012).
vascular malformation (1 paper, 2023). A non-neoplastic disorder that is the result of defects of vascular morphogenesis. "Recent studies have found that CDH11 is associated with vascular malformations." (PMID 37794518, 2023).
tumor (117 papers, 2004 to 2025). "Osteoblasts can rewire intratumoral steroidogenesis to maintain tumor growth in the presence of androgen deprivation, and androgen deficiency can increase adhesion molecules such cadherin 11, facilitating tumor cell/osteoblast interactions." (PMID 41465319, 2025). "VCAN, a major ECM component associated with tumor progression, was inhibited, while CDH11 was activated, highlighting ERβ’s ability to modulate cell adhesion and migration." (PMID 40647431, 2025). "Recently, in mouse models of PDAC, is has been demonstrated that Cdh11 deficiency alters the molecular profile of fibroblasts, reduces the expression of immunosuppressive cytokines and increases the anti-tumor immunity." (PMID 39575252, 2024). "Loss of CDH11 can lead to a less metastatic phenotype, that is less responsive to Wnt ligands in the tumor microenvironment." (PMID 38875295, 2024). "Of note, CAFs 1 and 3 mainly differ by the expression of cadherin-11, whose expression has been associated to anti-tumor immune response in a genetic mouse model of PDAC." (PMID 39575252, 2024). "In PDAC, it is primarily expressed by CAFs, and it was recently shown that Cdh11 deficiency induces antitumor immunity, reduces immunosuppression, and increases survival in tumor bearing mice." (PMID 37954069, 2023). "In general, tumor cells exhibiting high CDH11 expression, as indicated by high H‐score, are associated with high percentage of CDH11 positive cells in the tumor region (R2 = 0.78)." (PMID 37558205, 2023). "Despite several studies reporting on the involvement of CDH11 in multiple tumors, understanding of the signaling mechanisms underlying the role of CDH11 in tumor growth and metastasis remain elusive." (PMID 37558205, 2023). "Cdh11 deficiency in the tumor microenvironment also altered the transcriptional profile of neutrophils." (PMID 37954069, 2023). "Knowledge of immune cell subtypes and genes found as altered in the TME as a result of a Cdh11-deficiency and their relationship to tumor prognosis will provide a basis for further development of novel therapies for PDAC." (PMID 37954069, 2023). "CDH11 gene methylation was associated with tumor invasion and metastasis, suggesting that deletion of CDH11 gene expression caused by DNA methylation was involved in the occurrence and development of a variety of tumors." (PMID 33442417, 2021). "In GC, it was reported that CDH11 is associated with tumor progression and prognosis via regulating adhesion-related pathways." (PMID 32685527, 2020). "The mutation frequencies of Akap9, Cdh11, and Muc4 are less than 7% in the TCGA tumor database, whereas their mutation rates are higher than 85% in the murine OSCC cell lines analyzed." (PMID 33302499, 2020). "Subgroup analysis revealed that CDH11 overexpression is dramatically related to the poor prognosis of GC patients who are at T3 and T4 stages or grade 3 or have a high tumor mutation burden (TMB)." (PMID 32685527, 2020). "The findings of this report reflected the important role of CDH11 in GC and revealed an underlying interaction between CDH11 and tumor immune response." (PMID 32685527, 2020). "In particular, cadherin-11 is upregulated during tumour and inflammatory cell invasion, but the mechanisms underlying cadherin-11 stimulated cell migration are still incompletely understood." (PMID 26952325, 2016). "The spread of tumor volumes across the various time points is narrowed in mice that have lost both Cdh11 alleles." (PMID 20421947, 2010). "These analyses describe a significant decrease in tumor volume as Cdh11 alleles are lost (p = 0.016)." (PMID 20421947, 2010). "The CAFs have been implicated in tumor development, and CDH11 may be a promising therapeutic target for both hybrid EMT cells and CAFs." (PMID 39739317, 2025). "They found that cadherin 11 (CDH11) expression was associated with CAF pro-tumor activity, which could be inhibited by an anti-CDH11 antibody." (PMID 36598557, 2023).
tumor (continued). "In summary, our data suggests that Cdh11 deficiency significantly alters the fibroblast and immune microenvironments and contributes to the reduction of immunosuppressive cytokines, leading to an increase in anti-tumor immunity and enhanced survival." (PMID 37954069, 2023). "In addition, loss of CDH11 impaired the migratory capacity of tumor cells as shown using a 2D wound healing assay." (PMID 37558205, 2023). "Specifically, high levels of CDH11 expression have been linked to poor prognosis in gastric cancer and triple-negative breast cancer, yet it maintains a pro-apoptotic tumor suppressor role in others." (PMID 33192560, 2020). "Since tumor “growth” results from an imbalance between cell death and proliferation, we examined cell proliferation and cell death in TAg-RB tumors of mice with normal Cdh11 alleles versus mutated Cdh11 alleles." (PMID 20421947, 2010). "However, since these tumors arise from fewer tumor-initiating cells, we conclude that tumor growth per initiating cell was greater in mice with mutant Cdh11 alleles." (PMID 20421947, 2010). "It is possible that Cdh11 loss affects the expression of the TAg transgene in this murine model, or that it affects development of the subpopulation of Müller glia that gives rise to the TAg-RB tumours." (PMID 20421947, 2010). "We show that Cdh11 loss impacts the number of tumors that develop initially, and that it significantly increases the average tumor volume at PND84 per tumor initiating cell defined at PND8 in animals with mutant Cdh11 alleles with respect to animals with wild type alleles." (PMID 20421947, 2010). "To quantify tumor-initiating cells with respect to retinal area, we determined the ratio of TAg-positive cells per retinal area, which showed a significant reduction correlated with Cdh11 genomic loss (p = 0.01)." (PMID 20421947, 2010). "The similarity of tumor volume at PND84 suggests faster tumor growth may be occurring in mice with mutant Cdh11 alleles, considering that fewer multifocal tumors were initially present at PND28." (PMID 20421947, 2010). "This suggests that Cdh11 deficiency in CAFs may alter the tumor’s immune profile." (PMID 37954069, 2023). "Therefore, loss of homotypic engagement and cleavage of CDH11 may affect several pathways through β‐catenin and potentially other effectors, ultimately, affecting tumor growth and metastatic potential." (PMID 37558205, 2023). "CDH11 not only acts as an effector molecule but also influences tumor cell function by interfering with BCAA metabolism and activating the mTOR pathway." (PMID 39739317, 2025). "In this study, we found that CDH11 can contribute to BC progression based on big data analysis and demonstrated that inhibition of CDH11 altered tumor growth of advanced BC in vivo." (PMID 41263259, 2025). "In our study, the CDH11 inhibitor specifically targeted hybrid EMT tumor cells and activated the cGAS‐STING pathway, Thereby, the induction of apoptosis in these cells simultaneously stimulates immune cell activation." (PMID 39739317, 2025). "CDH11 exerts tumor-suppressive effects through pathways such as Wnt/β-catenin, AKT/Rho A, and NF-κB." (PMID 40001597, 2025). "Among these, CDH11, a cadherin family member located on Chromosome 16q22.1, emerged as a potential tumor suppressor in CRC." (PMID 40001597, 2025). "We also consider further investigation into the activation of the immune response within the tumor following CDH11 inhibition‐mediated cGAS‐STING activation." (PMID 39739317, 2025). "In contrast to the in vitro experimental results, percutaneously evaluated tumor size was significantly smaller at 4 weeks in xenograft tumors derived from both sh#1 and sh#2 CDH11 KD cells compared with shCtrl cells." (PMID 41263259, 2025). "CDH11 is highly expressed in cancer‐associated fibroblasts, which form part of the tumor microenvironment (TME), and inhibition of CDH11 inhibited tumor migration in vivo." (PMID 41263259, 2025).